ICOS (inducible T cell costimulator)
Diseases named in the same sentence as ICOS in open-access papers (continued):
Sharing a sentence is not in itself a finding about the gene and the disease.
graft versus host disease (1 paper, 2016). An immune system disorder that occurs after allogeneic hematopoietic stem cell transplant and is a reaction of donor immune cells against host tissues. "Together, these data suggest that ICOS blockade may be more beneficial in combination with traditional drugs (i.e., cyclosporine) used to ameliorate graft-versus-host disease (GVHD)." (PMID 27559335, 2016).
HELLP syndrome (1 paper, 2022). A life-threatening condition that can potentially complicate pregnancy. "A reduced number of ICOS-expressing peripheral T cells were determined in patients with spontaneous preterm labor, preeclampsia and HELLP syndrome." (PMID 36078100, 2022).
hepatitis B (1 paper, 2024). "Previous reports on changes in Tfh cells and ICOS expression after hepatitis B vaccination in individuals with HBsAg seroclearance focused on changes during the Peg-IFNα-treatment period." (PMID 38555445, 2024).
herpes infection (1 paper, 2020). "Our transcriptome profiling data identified the transcription factors ICOS and PRDM1 (BLIMP-1) as cooperative regulators of the co-inhibitory (exhaustion) module identified in antiviral CD8+ T cells associated with asymptomatic herpes infection." (PMID 32796943, 2020).
HIV-1 infection (1 paper, 2022). The type species of lentivirus and the etiologic agent of acquired immunodeficiency syndrome (AIDS). "Our data suggests that HIV-1 infection drives the expansion of cTfh cells, which in turn leads to perturbations of B cell differentiation through ICOS signaling during acute infection stage." (PMID 35222430, 2022). "The expansion of TLM and PBs may be the synergism of ICOS+cTfh or IL-21+ICOS+cTfh cells with other factors, such as immune activation and chronic inflammation after HIV-1 infection." (PMID 35222430, 2022). "However, the correlation between the elevated level of ICOS+cTfh or IL-21+ICOS+cTfh cells with memory B cell subsets during acute HIV-1 infection stage in our results indicated that signaling via ICOS after cTfh activation may drive the memory B cell perturbation as early as primary infection stage." (PMID 35222430, 2022). "It seems likely that ICOS rather than CD40L signaling is more critical for the disruption of B cell development by cTfh cells during HIV-1 infection, especially in acute infection stage." (PMID 35222430, 2022). "We also observed a similar result that the negative association trends between the frequency of IL-21+ICOS+cTfh cells and CD4+T cell count in both acute and chronic HIV-1 infection stage." (PMID 35222430, 2022). "Association analyses showed that the levels of ICOS+cTfh and IL-21+ICOS+cTfh cells were negatively correlated with those of AM, CM, RM cells, and positively correlated with those of NM cells in AHI but not chronic HIV-1 infection stage (CHI)." (PMID 35222430, 2022).
immunotoxicity (1 paper, 2020). "Interestingly, in addition to inflammatory responses, which were considered to be the main cause of immunotoxicity, immunosuppressive responses, such as the expansion of ICOS+ Treg cells and production of immunosuppressive cytokine, IL-10, occurred concurrently." (PMID 33193321, 2020).
Impaired glucose tolerance (1 paper, 2022). An abnormal resistance to glucose, i.e., a reduction in the ability to maintain glucose levels in the blood stream within normal limits following oral or intravenous administration of glucose. "Children with impaired glucose tolerance and T1D exhibit a higher frequency of CXCR5+PD-1+ICOS+, CD4+CXCR5+, and CD4+CXCR5+ICOS+ circulating follicular helper T cells (Tfh)." (PMID 36704045, 2022).
Intellectual disability (1 paper, 2018). "Several potentially pathologic genes within the deleted region were of interest including the intellectual disability gene SATB2 and the CD28/CTLA4/ICOS immune gene cluster." (PMID 30087679, 2018).
ischemia (1 paper, 2025). A hypoperfusion of the BLOOD through an organ or tissue caused by a PATHOLOGIC CONSTRICTION or obstruction of its BLOOD VESSELS, or an absence of BLOOD CIRCULATION. "ICOS knockout protects brain tissues from ischemia injuries and inhibits T cell–induced cytokines." (PMID 40536592, 2025).
Jaundice (1 paper, 2019). Yellow pigmentation of the skin due to bilirubin, which in turn is the result of increased bilirubin concentration in the bloodstream. "When Tregs were further divided into ICOS+ and ICOS−Tregs, only ICOS−Treg percentage and density were positively associated with jaundice-free survival (p = 0.013 and 0.026, respectively)." (PMID 31355166, 2019).
keloid (1 paper, 2020). An irregularly shaped, elevated mark on the skin caused by deposits of excessive amounts of collagen during wound healing. "Treg markers, FOXP3 and TGFβ1, and T-cell activation measure ICOS, were up-regulated in lesional keloid versus normal skin (P<0.05 for TGFβ1)." (PMID 33329590, 2020).
latent syphilis (1 paper, 2023). A stage of syphilis characterized by the serologic evidence of infection by Treponema pallidum without evidence of accompanying signs or symptoms related to the disease. "However, only the percentages of ICOS+ Tfh and effector memory Tfh cells showed significant increases in secondary syphilis patients and decreases in latent syphilis patients." (PMID 37901207, 2023). "Thus, the percentages of ICOS+ and PD-1+Tfh cell subsets to total Tfh cells were investigated in secondary syphilis and latent syphilis patients." (PMID 37901207, 2023). "Dysregulated ICOS+ Tfh or effector memory Tfh cells may play an important role in immune evasion in latent syphilis patients." (PMID 37901207, 2023).
leukoplakia (1 paper, 2021). A white patch or plaque on a mucous membrane that cannot be characterized clinically or pathologically as any other disease. "In addition, CYLD, CARD11, TCF7, CCR7, KLRB1, CD28, and ICOS were other significantly highly expressed genes among the proliferative leukoplakia subgroup (log2 fold changes, 0.65–3.51; all Padj = 0.001)." (PMID 36860910, 2021). "Another gene of interest with overexpression among proliferative leukoplakia samples was inducible T-cell costimulator (ICOS), which codes for a T-cell costimulatory receptor that promotes T-cell proliferation, chemokines, and facilitates B-cell antibody secretion." (PMID 36860910, 2021).
Lewis lung carcinoma (1 paper, 2022). "A similar study highlighted that ICOS expression was shown to be an indicator of T cell-mediated immune responses following treatment with a STING agonist in Lewis lung carcinoma murine models." (PMID 35366537, 2022).
liver cirrhosis (1 paper, 2020). "In contrast, CD28 and CD11a were not significantly altered on CD4+ effector T cells and regulatory T cells, whereas ICOS was only upregulated on CD4+ regulatory T cells of patients with liver cirrhosis." (PMID 33574809, 2020).
lymphoid tumor (1 paper, 2021). "On the contrary, the antagonistic monoclonal antibody against ICOS can not only inhibit the lymphoid tumor cells expressing ICOS, but also inhibit the immunosuppressive Treg." (PMID 34917609, 2021).
membranous nephropathy (1 paper, 2018). "Significantly higher frequency of CD4+/CXCR5+, CD4+/CXCR5+/ICOS+ and CD4+/CXCR5+/PD-1+ TFH cells, and higher serum levels of IL-17A, IFN-γ, IL-2, IL-10, IL-4 and IL-21 were detected in hepatitis B virus-associated membranous nephropathy patients compared to the healthy controls." (PMID 28770269, 2018).
metabolic dysfunction-associated steatohepatitis (1 paper, 2023). Metabolic dysfunction-associated steatohepatitis (MASH, formerly known as nonalcoholic steatohepatitis or NASH) is a type of fatty liver disease. "In this study, we investigated the involvement of ICOS/ICOSL dyad in modulating macrophage functions during the evolution of metabolic dysfunction-associated steatohepatitis (MASH)." (PMID 38077334, 2023).
metastatic cancers (1 paper, 2025). A carcinoma which has spread from the original site of growth to another anatomic site. "Thus, ICOS and ICOSL high expression alone were not prognostic markers for metastatic cancers and do not predict better outcomes following ICI administration." (PMID 40297627, 2025).
myeloid leukemia (1 paper, 2019). A clonal proliferation of myeloid cells and their precursors in the bone marrow, peripheral blood, and spleen. "As previously demonstrated by our group, myeloid leukemia cells can provide direct costimulation via CD80, CD86, and ICOS-LG molecules, and these malignant blasts are proficient in utilizing elaborate immune evasion strategies including the adaptive resistance and T-cell exhaustion." (PMID 31406210, 2019).
neuropathy (1 paper, 2017). A disorder affecting the nervous system that manifests with pain, tingling, numbness, and/or muscle weakness. "Size of the non-NOD-derived genomic regions around the mutated genes expressing ICOS and ICOS/ICOS ligand in non-obese diabetic congenic mice, and comparison of these intervals to known candidate regions for type 1 diabetes (Idd loci) and neuropathy (QTLs)." (PMID 28424681, 2017).
Nicotine addiction (1 paper, 2025). "Among these, the TGF-beta signaling pathway, T cell receptor signaling pathway, and Nicotine addiction pathway were highly enriched (p < 0.01) enriched involving relevant genes (PITX2, ID4, BMP4, DLG1, IKBKB, ICOS, GRIA3, and SLC17A6)." (PMID 40496916, 2025).
non-Hodgkin lymphoma (1 paper, 2025). Distinct from Hodgkin lymphoma both morphologically and biologically, non-Hodgkin lymphoma (NHL) is characterized by the absence of Reed-Sternberg cells, can occur at any age, and usually presents as a localized or generalized lymphadenopathy associated with fever and weight loss. "In HIV-positive individuals at risk for developing non-Hodgkin lymphoma (pre-NHL), CD8+PD-1+CD27+CXCR4− T-cells positively correlate with CD4+FoxP3+PD-1+ T-cells expressing CD27, CD28, ICOS, and CD71." (PMID 41148820, 2025).
parasite (1 paper, 2018). "To understand the possible involvement of ICOS in the lethality of blood stage PbA infection, we first established parasite infection in BALB/c mice by intravenous injection of 1 × 104 parasitic RBCs." (PMID 29892278, 2018).
periodontitis (1 paper, 2024). An acute or chronic inflammatory process that affects the tissues that surround and support the teeth. "The JK-microniche was most often PD-L1+ in contrast to SK-localized tertiary lymphoid structures, which more often contained mixed active (ICOS+) and exhausted (PD-1+) populations in periodontitis." (PMID 38876998, 2024). "Phenotypic analysis revealed an immunosuppressed JK-microniche (PD-L1+ epithelial and stromal cells) and evidence for SK-localized tertiary lymphoid structures containing mixed active (ICOS+) and exhausted (PD-1+) populations in periodontitis." (PMID 38876998, 2024).
pneumonitis (1 paper, 2025). An inflammatory process affecting the lung parenchyma. "The increase in the frequency of ICOS+CD4+ T cells in the blood was characteristic not only of patients with pneumonitis but also of those with hematological and skin irAEs." (PMID 40198121, 2025). "Because the current cohort was small, unlike in the Spearman’s rank correlation coefficient analysis, neither the change in ICOS+CD4+ T cells nor in CXCL13 was identified as an independent risk factor for irAEs (or pneumonitis) in the multivariate analysis." (PMID 40198121, 2025). "While the proportions of both CD4+ T cells and CD8+ T cells were not altered by the therapy, the expression of ICOS in peripheral CD4+ T cells was significantly upregulated in patients with the irAE pneumonitis, but not in those without any irAEs." (PMID 40198121, 2025). "An increased frequency of ICOS+CD4+ T cells was a better predictor for pneumonitis development than those of CXCL13 or IL-6 levels, and combined assessment of both changes in ICOS+CD4+ T cells and CXCL13 levels had an even greater predictive value for later development of pneumonitis." (PMID 40198121, 2025).
polyp (1 paper, 2016). A usually exophytic mass attached to the underlying tissue by a broad base or a thin stalk. "IL-21-expressing CD8+ T cells in polyp tissues expressed higher CXCR5, PD-1, and ICOS levels than cells in control tissues and showed significantly higher T-bet and Bcl-6 expression levels compared with IL-21−CD8+ T cells." (PMID 27468819, 2016). "Some of the IL-21-producing CD8+ T cells in polyp tissues co-expressed IFN-γ, CXCR5, PD-1, ICOS, T-bet and Bcl-6, which display the T follicular helper (Tfh) cell functionality." (PMID 27468819, 2016). "Moreover, the percentage of CXCR5+IL-21+, ICOS+IL-21+ and PD-1+IL-21+ cells in CD8+ T cells was higher in polyp tissues than in control sinonasal tissues (P < 0.01)." (PMID 27468819, 2016). "The expression of CXCR5, PD-1 and ICOS on CD8+ T cells in polyp tissues was significantly increased compared with control tissues (P < 0.01), and some IL-21-expressing CD8+ T cells were found to co-express CXCR5, ICOS and PD-1 in polyp tissues." (PMID 27468819, 2016).
prostate tumors (1 paper, 2022). "Although ADT was associated with significantly higher levels of ICOS+ and GrB+ cells, which may represent an activated T cell subset, greater immune cell infiltration is not found in prostate tumors after ADT." (PMID 36506053, 2022).
psoriasis vulgaris (1 paper, 2016). Plaque psoriasis is the most common presentation of psoriasis. "Thus, we detected the expression of ICOS, PD-1, HLA-DR, and Ki-67 on cTfh cells and secretion of IL-21, IL-17, IFN-γ, and IL-10 by cTfh cells in patients with psoriasis vulgaris." (PMID 27774460, 2016).
pulmonary TB (1 paper, 2014). "To determine the distribution of circulating Tfh cells in human TB, we measured the frequencies of Tfh cells exvivo and following TB - antigen or polyclonal stimulation in pulmonary TB (PTB; n = 30) and latent TB (LTB; n = 20) individuals, using the markers CXCR5, PD-1 and ICOS." (PMID 25343703, 2014).
renal carcinoma (1 paper, 2025). A carcinoma arising from the epithelium of the renal parenchyma or the renal pelvis. "In renal cancers, the main contributors to PC-1, the axis separating healthy and sick – were the CD86, TIGIT, ICOS, and BTLA genes." (PMID 40788962, 2025).
renal fibrosis (1 paper, 2023). A final common manifestation of a wide variety of chronic kidney diseases characterized by glomerulosclerosis and tubulointerstitial fibrosis. "Targeting the ICOS-signaling pathway network could reduce TFH cell infiltration and alleviate renal fibrosis." (PMID 37628716, 2023).
Schistosomiasis japonica (1 paper, 2015). Schistosomiasis caused by Schistosoma japonicum. "Next, we compared the frequencies of total peripheral memory Tfh cells (CXCR5+CD45RA-CD4+ T cells) and activated peripheral memory Tfh cells (PD-1+ICOS+Tfh cells) among CD4+ T or total peripheral memory Tfh cells in 50 patients with schistosomiasis japonica to 50 healthy controls." (PMID 26284362, 2015).
Sézary syndrome (1 paper, 2023). "Immunohistochemistry analysis revealed that ICOS protein was present in the majority of 52 skin biopsy samples from individuals with mycosis fungoides and Sézary syndrome." (PMID 36765704, 2023). "Flow cytometry analysis showed that circulating tumor cells in all patients with Sézary syndrome strongly expressed ICOS." (PMID 36765704, 2023).
skin infection (1 paper, 2023). An inflammatory process affecting the skin, caused by bacteria, viruses, parasites, or fungi. "To measure both the antigen-dependence, as well as the kinetics of Blimp1/ICOS expression during viral skin infection, we quantified the frequency of effector P14 CD8+ T cells co-expressing ICOS and Blimp1 (ICOS+Blimp1+) at different time points following VacV skin infection (+/- Ag)." (PMID 37402742, 2023).
syphilis (1 paper, 2023). A contagious bacterial infection caused by the spirochete Treponema pallidum. "The percentage of total Tfh cells was significantly higher in secondary syphilis patients compared to HCs across various subsets, including ICOS+ Tfh, PD-1+ Tfh, resting Tfh, effector Tfh, naïve Tfh, effector memory Tfh, central memory Tfh, Tfh1, Tfh2, and Tfh17 cells." (PMID 37901207, 2023). "Conversely, the ICOS+Tfh cell subset exhibited significant differences across all three group comparisons (HCs vs. Secondary syphilis patients p = <0.0001, HCs vs. Latent syphilis patients p = 0.0035, Secondary syphilis patients vs. Latent syphilis patients p = <0.0001)." (PMID 37901207, 2023).
Trematode Infections (1 paper, 2013). Infections caused by infestation with worms of the class Trematoda. "In summary, alongside its role in controlling CD4+ Teff-cell responses, ICOS co-stimulation promotes the expansion and maintenance of Foxp3+ Treg cells in both nematode and trematode infections." (PMID 23319295, 2013). "Thus, upregulation of ICOS by Foxp3+ Treg cells is a common feature of both nematode and trematode infections." (PMID 23319295, 2013).
tuberculosis (1 paper, 2014). A chronic, recurrent infection caused by the bacterium Mycobacterium tuberculosis. "To study the distribution of Tfh cells in TB infections, we examined Mtb antigen-specific induction Tfh cells subsets (defined as CD4+ CXCR5+ PD-1+ ICOS− or CD4+ CXCR5+ PD-1− ICOS+ or CD4+ CXCR5+ PD-1+ ICOS+) in PTB and LTB individuals in an area highly endemic for tuberculosis." (PMID 25343703, 2014).